TCF4 (transcription factor 4)
Diseases named in the same sentence as TCF4 in open-access papers (continued):
Sharing a sentence is not in itself a finding about the gene and the disease.
colon carcinoma (continued). "TCF-4, as a component of the Wnt pathway, also works as a tumor suppressor in colon cancer and is involved in papillary thyroid carcinoma via regulation of HCP5." (PMID 35885958, 2022). "An example of a transcription factor with increased activity in colon cancer cells is TCF7L2 (TCF4), the main transcription factor activated by Wnt signaling." (PMID 36067202, 2022). "It is worth noting that previous ChIP-Seq studies on colon cancer cells found β-catenin-TCF4 on the genomic regions of HDAC1 and DNAJB1." (PMID 36551548, 2022). "miR-137 acts as a tumor suppressor, which inhibits the proliferation, migration, and invasion of colon cancer cells by targeting TCF4." (PMID 34036176, 2021). "The RBM5 anti-sense transcript (lncRNA RBM5-AS1) sustains the function of colon cancer-initiating cells through the organization of a transcriptional complex containing β-catenin and transcription factor 4 (TCF4)." (PMID 32429086, 2020). "In colon cancer cells, DAXX was down-regulated, and the interaction between DAXX and Tcf4 was strongly associated with the proliferation of colon cancer cells, indicating that DAXX functions as a suppressor of tumor proliferation." (PMID 31942198, 2020). "As is well-known, TCF4 promotes disease progression in diverse tumors, such as breast cancer, colon cancer and prostate cancer." (PMID 32714094, 2020). "Strong positive correlation was observed between the abundance of β-catenin, TCF4 and RelA in both normal and colon carcinoma tissue samples." (PMID 31351496, 2019). "The difference between the average H-scores of β-catenin and TCF4 in colon carcinoma samples was highly statistically significant as to that of the normal samples." (PMID 31351496, 2019). "(A) Notched box plots showing the distribution of H-scores of β-catenin and TCF4 in normal (n = 22) and colon carcinoma samples (n = 45); Mann–Whitney U-values were calculated from H-scores." (PMID 31351496, 2019). "In order to induce cytotoxicity in colon cancer cells, targeting the β-catenin:TCF4 interaction is critical." (PMID 31608135, 2019). "In the present study, we have deciphered the role of γ-Mangostin in inhibiting the colon cancer growth by targeting TCF4, thereby hindering β-catenin:TCF4 interaction." (PMID 31608135, 2019). "Proteasomal degradation of TCF4 has been reported earlier in colon cancer cells after resveratrol treatment, followed by decreased TCF4 protein expression." (PMID 31608135, 2019). "Collectively, these results strongly indicate that the β-catenin/TCF4 complex is a direct regulator of NRF3 gene induction in colon cancer cells." (PMID 31288376, 2019). "We herein describe that NRF3 upregulation is induced by the β-catenin/TCF4 complex in colon cancer cells." (PMID 31288376, 2019). "Sporadic colon cancers are mostly caused by genetic mutations of APC and β-catenin which results in β-catenin stabilization and formation of the β-catenin/TCF4 complex." (PMID 31608135, 2019). "Previous studies on the mechanism of Ln-γ2 expression had demonstrated that its gene and protein expression are up-regulated in gastric and colon cancer cells by transcriptional factor 4 (TCF4)/β-catenin and/or Wnt-5a." (PMID 30626121, 2019). "This clearly shows that γ-Mangostin also affect the stemness property in colon cancer cells by inhibiting the β-catenin/TCF4 interaction." (PMID 31608135, 2019). "The 1,25D ligand-activated VDR in colon carcinoma cells competes with a β-catenin binding member (Tcf4) for β-catenin binding." (PMID 30314996, 2018). "In adult mice with a dominant mutated APC gene, conditional knockout of TCF4 significantly enhances colon tumor formation, indicating that TCF4 is a tumor suppressor." (PMID 29975781, 2018). "With disruptions in the Wnt signaling pathway found in the majority of colon cancer tumors it is nonetheless to be expected that dysregulation of TCF4 has a part to play in colon cancer initiation and/or progression." (PMID 29975781, 2018).
colon carcinoma (continued). "This function occurs in the presence of the β-catenin/TCF4 complex, demonstrating a mechanism how Smad2 functions as a tumor promoter in the late stages of colon cancer." (PMID 28430641, 2017). "Daxx associates with TCF4 in DNA-bound complexes and co-upregulates the β-catenin/ TCF4-mediated gene expression in colon cancer cells." (PMID 28430641, 2017). "Recently, a small-molecule inhibitor of the β-catenin/TCF4 interaction called LF3 has been shown to diminish Wnt-dependent biologic characteristics of colon cancer cells, inhibit their self-renewal capacity and induce their differentiation." (PMID 28139702, 2017). "We show that RHBG is expressed in the colon cancer SW480 cells bearing an APC mutation and that its expression is also dependent on TCF4/ β-catenin." (PMID 26029888, 2015). "A recent study supports that TCF4 knockdown sensitizes chemotherapeutic agent-mediated cytotoxicity in colon cancer cells." (PMID 25961950, 2015). "Resveratrol increases phosphorylation of TCF4 and decreases the expression of TCF4 through proteasomal degradation in colon cancer cells." (PMID 25961950, 2015). "Wnt signaling regulates β-catenin stabilization, which accumulates in the cytoplasm and binds to T-cell factor 4 (TCF4) in colon cancer." (PMID 25961950, 2015). "Previous reports have shown that galectin-3 mediates nuclear β-catenin accumulation and subsequently increases TCF4 transcriptional activity followed by the upregulation of its target genes, such as cyclin D1 and c-myc, in colon cancer cells." (PMID 24303084, 2013). "In that study, TCF4 overexpression was related to an unfavorable prognosis whereas nuclear β-catenin in late-stage colon cancer predicted a favorable outcome." (PMID 23224985, 2013). "We show that compared to β-catenin knockdown, Tcf-4 knockdown significantly inhibits cell proliferation, induces cell apoptosis, and enhances the chemosensitivity of colon cancer cells through the upregulation of FOXO4 transcriptional activity." (PMID 23029137, 2012). "In conclusion, we have shown that targeted inhibition of β-catenin/Tcf-4 signaling inhibits cell proliferation, induces apoptosis, and enhances chemosensitivity of colon cancer cells." (PMID 23029137, 2012). "We further investigated the mechanisms involved in the different efficacies observed with β-catenin and Tcf-4 knockdown in colon cancer cells." (PMID 23029137, 2012). "Previous studies suggest that FH535 inhibits the transcription of TCF4, which is a critical protein regulating gene expression in colon cancer cells." (PMID 22984505, 2012). "BC21 blocks the clonogenic activity of colon cancer cells, down-regulates c-Myc and cyclin-D1 expression, and represents a new potential anticancer agent that targets TCF4/beta-catenin interaction." (PMID 22910040, 2012). "We have shown that Tcf-4 knockdown induces a significantly stronger inhibition of cell proliferation, induction of apoptosis, and enhancement of chemosensitivity in colon cancer cells compared to β-catenin knockdown." (PMID 23029137, 2012). "In the present study, we specifically focused on comparing the efficacies of β-catenin knockdown and Tcf-4 knockdown in colon cancer cells, and investigated the possible molecular mechanisms responsible for these effects." (PMID 23029137, 2012). "Our results show that, compared to β-catenin knockdown, Tcf-4 knockdown more effectively inhibited colony formation, induced apoptosis, and increased 5-FU and oxaliplatin-mediated cytotoxicity in colon cancer cells." (PMID 23029137, 2012). "We reported that colon cancer cells, via a soluble factor, activate macrophages to secrete IL1β, which in turn promotes β-catenin/TCF4 transcriptional activity in the cancer cells and stimulates their growth." (PMID 23029025, 2012). "Human transcription factor 4 (hTCF-4), a TCF family member that is expressed in human colonic epithelium and colon carcinoma cells, transactivates transcription only when associated with β-catenin." (PMID 22168384, 2011).
colon carcinoma (continued). "Together these data suggest that long-range chromatin loops position distal enhancer elements to the MYC promoter and that this conformation is poised to recruit ß-catenin/TCF4 complexes to regulate MYC expression in colon cancer cells." (PMID 21533051, 2011). "ß-Catenin/TCF4 complexes were shown to regulate MYC expression in colon cancer cells through two proximal Wnt/ß-catenin responsive enhancers (WREs)." (PMID 21533051, 2011). "The elevated MYC levels in colon cancer cells are attributed in part to ß-catenin/TCF4 transcription complexes that are assembled at proximal Wnt/ß-catenin responsive enhancers (WREs)." (PMID 21533051, 2011). "Nuclei of human APC-/- colon cancer cells contain stable β-catenin-TCF-4 complexes for target gene activation." (PMID 22022540, 2011). "Our previous work implicated a role for ß-catenin/TCF4 complexes in mediating the interaction between the MYC 3′ WRE and the MYC promoter in colon cancer cells." (PMID 21533051, 2011). "ß-Catenin recruitment to enhancer elements in colon cancer cells occurs predominantly through interactions with the T-cell factor family member TCF4." (PMID 21533051, 2011). "Activity of β-catenin and TCF-4, key components of the Wnt signaling pathway, is frequently deregulated in colon cancers, resulting in activation of genes whose dysregulation has significant consequences on tumor development." (PMID 20711340, 2010). "In addition, circ0075829, which is highly expressed in colon cancer, can up-regulate TCF4 expression by sponging miR-330-5p, thereby inhibiting ferroptosis and promoting proliferation in colon cancer." (PMID 40628711, 2025). "Moreover, curcumin treatment suppressed the growth of colon cancer cells in the mouse model and an antitumor effect was mediated by the downregulation of β-catenin and TCF4 via the downregulation of miR-130a." (PMID 39684513, 2024). "In this study, we treated patient derived GBM cultures with TSA and SAHA and demonstrated their ability to strongly reduce TCF4 levels, as previously shown in colon cancer; thus, impairing cell stemness and even sensitizing them to the standard chemotherapeutic treatment with TMZ." (PMID 35454804, 2022). "Previous studies have shown that when HCT-116 cells were treated with celecoxib, a selective cyclooxygenase-2 inhibitor, Tcf-4 expression was significantly inhibited and Wnt/β-catenin and Tcf-4 expression was blocked, reducing human colon cancer cell proliferation." (PMID 34976156, 2022). "Since histone deacetylase inhibitors (HDI) have been reported to strongly reduce TCF4 levels in colon cancer cells, we hypothesized that they could also exert a similar therapeutic action in GBM." (PMID 35454804, 2022). "Interestingly, depending on different tumor types, TCF4 functions as either an oncogene (diffuse large B-cell lymphoma) or tumor suppressor (medulloblastoma and colon cancer)." (PMID 33080033, 2020). "In colon cancer, Aspirin has been reported to inhibit the canonical Wnt/β-catenin signaling pathway by inducing β-catenin phosphorylation resulting in the downregulation of nuclear β-catenin and TCF4 signaling." (PMID 31824307, 2019). "Here, we aimed to determine the effects of γ-Mangostin on colon cancer growth and elucidated the mechanism, which we have identified to be inhibiting the β-catenin-TCF4 interaction by inhibiting the transcriptional activity of TCF4." (PMID 31608135, 2019). "Furthermore, TREM2 increases β-catenin phosphorylation by activating GSK-3β, which suppresses β-catenin accumulation and TCF4 transcriptional activity, resulting in the downregulation of tumorigenicity in colon cancer cells." (PMID 31489935, 2019). "β-catenin and TCF4 interaction can also influence stemness signature genes in colon cancer cells." (PMID 31608135, 2019). "Together, these data suggest that γ-Mangostin inhibits colon cancer growth through targeting TCF4." (PMID 31608135, 2019).
colon carcinoma (continued). "We found that TREM2 inhibited the canonical Wnt1/β-catenin signaling pathway, which in turn suppressed the proliferation and tumorigenicity of HT29 colon cancer cells by inhibiting β-catenin/TCF4 transactivation activity, resulting in the suppression of cell proliferation and DNA synthesis." (PMID 31489935, 2019). "Combined, these studies collectively do not support the hypothesis that expression of PPARβ/δ is increased by APC/β-CATENIN/TCF4 signaling in colon cancer, as both the mouse and human models examined include those with defective APC signaling." (PMID 31602402, 2019). "In the TCF/LEF family, TCF4 was reported to be abundantly expressed in colon cancer cells." (PMID 31288376, 2019). "Vitamin D administration also induces the expression of E-cadherin, and thus inhibits EMT progression by modulating the β-catenin/TCF-4 axis, which exerts an opposite effect on the β-catenin signaling pathway, and thereby suppresses tumorigenesis and the metastasis of colon carcinoma cells." (PMID 30314996, 2018). "However, the expression of TCF4 in colon tumors has been shown to correlate to lower survival, indicating oncogenic properties of TCF4." (PMID 29975781, 2018). "We thus tested whether the transcriptional activity of β-catenin/TCF4 was induced by treating the colon cancer cell lines with MACRO-CM." (PMID 29462209, 2018). "Furthermore, in colon carcinoma cells, an active β-catenin-TCF4 complex is required for physiological targeting of SOX9." (PMID 28279198, 2017). "In colon cancer cells, TCF4/TCF7L2 is located in the nucleus with beta-catenin." (PMID 28536608, 2016). "Previous studies indicate that AR and TCF4 have overlapping interaction domains on β-catenin and the competitive binding of AR and TCF4 to β-catenin has been shown in both prostate and colon cancer cells." (PMID 26509262, 2015). "Indeed, ligand-bound AR decreases the transcriptional activity of TCF4 in prostate cancer, colon cancer, and neurons." (PMID 26207810, 2015). "In addition, the encyclopedia of DNA elements (ENCODE) data also showed that TCF4 binds to a region of the human ID2 promoter that is homologous to the mouse Id2 enhancer in HCT116, a Wnt-signaling activated colon cancer cell line." (PMID 26163528, 2015). "In addition, other groups revealed that RNF43 expression was also elevated in adenomas of the colon, that it is down-regulated by a dominant-negative form of Tcf4 in LS174 colon cancer cells, and that expression of RNF43 was induced by Wnt3a conditioned media." (PMID 24466159, 2014). "Our group has recently exposed the reciprocal regulatory mechanism between CCAT2 and the Wnt pathway and furthermore, various studies have shown a positive correlation of TCF4/β-catenin expression with chemoresistance to 5'FU, mostly in colon cancer, but also in BC." (PMID 24077681, 2013). "In line with this, it has been reported that TCF4 inhibits growth of colon cancer cells." (PMID 24202444, 2013). "In addition, the inhibition of the APC/β-catenin/TCF4 pathway in colon cancer cells by the forced expression of a transfected, dominant negative TCF4 variant also leads to increased SERCA3 expression." (PMID 24970132, 2012). "Surprisingly, these loops are not restricted to colon cancer cells, but are also found in cells that lack ß-catenin/TCF4 chromatin associated complexes." (PMID 21533051, 2011). "Interestingly, the MT1-MMP gene is up-regulated in colon carcinomas mediated by a direct interaction of β-catenin/TCF4 complex and their 5' flanking region, indicating that it is a direct target of Wnt pathway." (PMID 20515496, 2010). "Moreover, we identified relevant signaling pathways (FAK, Wnt, Notch) and transcription factors (Egr1, TCF4), as constituents of this regulatory circuit, which paves the way for a more efficient combinatorial targeting of colon cancer in the context of therapeutic resistance." (PMID 32477959, 2020).
colon carcinoma (continued). "Thus, the role of TCF4 in colon cancer is not yet fully understood and it may function as both a tumor suppressor and an oncogene." (PMID 29975781, 2018). "Therefore, the interruption of the β-catenin/TCF4 complex could be a potential target in the treatment of colon cancer." (PMID 25961950, 2015). "Therefore, we hypothesize that the upregulation of FOXO4 activity is responsible for the greater efficacy of Tcf-4 shRNA effects in colon cancer cells compared to β-catenin shRNA." (PMID 23029137, 2012). "Consequently, we conclude that the 1,25(OH)2D3/VDR-mediated increase in TCF-4 may have a protective role in colon cancer as well as diabetes and Crohn's disease." (PMID 19924301, 2009). "REV7 binds to WNT signal transducer T cell factor 4 (TCF4) and blocks TCF4-mediated transactivation of downstream target genes such as SLUG in colon cancer cells." (PMID 36980607, 2023). "Supporting this evidence, a previous study showed that ZIC5 interacts with the β-catenin/TCF4 complex to repress GLUT1 expression and regulate glucose metabolism in HCT 116 colon cancer cells." (PMID 36127329, 2022). "In colon cancer cells, nitrosylation of β–catenin results in the dissociation of the β–catenin/TCF4 complex, inhibiting TCF-4 transcriptional activity." (PMID 34947954, 2021). "siRNA-depletion of Syndecan-1, and upregulation of heparanase increased the colon cancer stem cell phenotype based on sphere formation assays and phenotypic marker analysis (Side-population, NANOG, KLF4, NOTCH, Wnt, and TCF4 expression)." (PMID 32477959, 2020). "Blocking β-catenin/TCF4 signaling using FH535 and CTNNB1-specific small interfering RNA decreased DCLK1 expression in HCT116 human colon cancer cells." (PMID 29254234, 2017). "Primary human colon cancer cells (CC14 and CC36) as well as metastatic colon cancer cells (mCC11) and a metastatic cell line (T84) were stably transduced with GFP+ dominant-negative TCF4 (dnTCF), Wnt1, or with control lentivectors." (PMID 26939070, 2016). "Several clinical studies have reported that TCF4/TCF7L2 is an indicator of poor prognosis or malignant potential in hepatocellular carcinomas and colon cancer." (PMID 28536608, 2016). "For gained VELs in colon cancer we observe an enrichment of TCF7L2, also known as TCF4, involved in many cancer types." (PMID 25477382, 2015). "Knockdown of TCF4 efficiently inhibited the TCF-reporter TOPFlash and growth arrest in colon cancer cells." (PMID 25961950, 2015). "Thus, the induction of TCF4 expression by 1,25(OH)2D3 may have a protective role in colon cancer." (PMID 24202444, 2013). "In this study, we compared the effects of Tcf-4 knockdown with β-catenin knockdown on cell proliferation, apoptosis, and chemosensitivity in SW480 and HCT116 colon cancer cells using adenoviral vector-mediated short hairpin RNA (shRNA)." (PMID 23029137, 2012). "Thus, the short-lived up-regulation of TCF-4 by 1,25(OH)2D3 in CaCo2 cells that we report, here, may facilitate 1,25(OH)2D3-induced apoptosis in cells with abundant β-catenin, that is analogous to butyrate in other colon cancer cell lines." (PMID 19924301, 2009). "We show that in a Tcf4-haploinsufficient background, the Tcf4 Lin-, but not the Tcf4 Lin+, cell population represents the cell of origin for colon tumors driven by deletion of Apc." (PMID 41889847, 2026). "c-Myc, Snai1, and Id1, but not Tcf4 and Id2, were found to be highly expressed in the colon cancer cell-derived CM-treated group compared to the control (Ctrl) group." (PMID 37996458, 2023). "TCF4 (also known as TCF7L2) is a transcription factor that is involved in the Wnt signalling pathway, and it has been found that constitutive activation of β-catenin/TCF4 can promote colon cancer development." (PMID 34321074, 2021).